FOXD1 (forkhead box D1)
Diseases named in the same sentence as FOXD1 in open-access papers (continued):
Sharing a sentence is not in itself a finding about the gene and the disease.
prostate carcinoma (10 papers, 2020 to 2025). A carcinoma that arises from epithelial cells of the prostate gland. "FOXD1 knockdown inhibited hypoxia-induced prostate cancer cell growth, which was mediated by glycolysis." (PMID 41214670, 2025). "Inhibition of glycolysis by 2-DG reversed the effect of FOXD1 overexpression on hypoxia-induced prostate cancer cell growth, implying the FOXD1 exerted its roles via regulating glycolysis." (PMID 41214670, 2025). "In conclusion, this study showed that FOXD1 was identified as a hypoxia-related gene and tumor promoter in prostate cancer." (PMID 41214670, 2025). "In the current study, we aimed to test the effect of FOXD1 on prostate cancer cell growth in response to hypoxia." (PMID 41214670, 2025). "The results indicate that glycolysis mediates the effects of FOXD1 on prostate cancer cell growth under hypoxia conditions." (PMID 41214670, 2025). "Despite FOXD1 has been found to be involved in several types of cancer, its role in mediating prostate cancer cells under hypoxia conditions is unclear." (PMID 41214670, 2025). "Under normoxia conditions, FOXD1 knockdown inhibited prostate cancer cell viability and colony formation, while FOXD1 overexpression exhibited the opposite effects." (PMID 41214670, 2025). "According to the databases, FOXD1 is significantly upregulated in prostate cancer tissues and further induced by intratumoral hypoxia." (PMID 41214670, 2025). "Since the roles of hypoxia-induced HK2 in prostate cancer cells have been widely reported, we mainly focused on FOXD1, and HK2 was only detected as a key glycolytic enzyme in the following experiments." (PMID 41214670, 2025). "Another study suggests that silencing of FOXD1 suppresses proliferation, migration, and invasion of the prostate cancer." (PMID 41214670, 2025). "Subsequently, the roles of FOXD1 in regulating prostate cancer cell growth under hypoxia conditions were evaluated." (PMID 41214670, 2025). "In this study, we aimed to test the effect of FOXD1 on prostate cancer cell growth in response to hypoxia." (PMID 41214670, 2025). "Our results showed that FOXD1 expression was upregulated in prostate cancer cell lines under hypoxia conditions compared with cells under normoxia conditions, based on the data analysis of GEO databases." (PMID 41214670, 2025). "Our experiments proved that protein level of FOXD1 was increased in prostate cancer PC-3 and 22Rv1 cells." (PMID 41214670, 2025). "In prostate cancer, FOXD1 knockdown inhibits cancer cell metastatic potential through its regulatory impact on β-catenin expression." (PMID 40999468, 2025). "It has been reported that in normal prostate tissue, FOXD1 was hardly expressed; however, it was highly expressed in prostate cancer cells and lymph node metastases, indicating the contribution of FOXD1 in prostate tumorigenesis." (PMID 36983712, 2023). "Overexpression of FOXD1 is related to abnormal cell proliferation and occurs in numerous human cancers, including cancers of the prostate, lung, and liver." (PMID 38092733, 2023). "The identification of FOXDs as candidate Wnt pathway activators is consistent with the recent observation that silencing of FOXD1 lowered β-catenin levels in prostate cancer cells and concomitantly decreased cell proliferation and invasion." (PMID 37011861, 2023). "A weighted correlation network analysis (WGCNA) of 201 patients in a TCGA prostate cancer dataset revealed hypermethylation of FOXD1 as an unfavorable marker for survival." (PMID 33785068, 2021). "In prostate cancer, down-regulation of FOXD1 affected the expression of cell cycle control genes and suppressed the androgen-independent growth of 22RV1 cells." (PMID 34269372, 2021). "FOXD1 knockdown inhibited hypoxia-induced prostate cancer cell growth." (PMID 41214670, 2025). "We determined whether FOXD1 is a hypoxia-related gene, and explored the roles of FOXD1 in prostate cancer cell growth and glycolysis." (PMID 41214670, 2025).
prostate carcinoma (continued). "Our results showed that FOXD1 expression was upregulated in prostate cancer." (PMID 41214670, 2025). "Moreover, inhibition of glycolysis by 2-deoxyglucose reversed the effect of FOXD1 overexpression on hypoxia-induced prostate cancer cell growth." (PMID 41214670, 2025). "Thus, we inferred that hypoxia upregulates FOXD1 expression by activating the Akt pathway in prostate cancer." (PMID 41214670, 2025). "Besides, FOXD1 mRNA levels were found to be increased in prostate cancer patients, as compared to normal individuals." (PMID 41214670, 2025). "Currently, FOXD1 has been found to be involved in the tumorigenesis of prostate cancer." (PMID 41214670, 2025). "Hypoxia exposure increased the expression of FOXD1 in prostate cancer." (PMID 41214670, 2025). "Knockdown of FOXD1 decreased the viability and colony formation of PC-3 and 22Rv1 cells, while overexpression of FOXD1 exhibited opposite effects, implying that FOXD1 might be a tumor-promoter in prostate cancer cells." (PMID 41214670, 2025). "Therefore, FOXD1 might be a potential therapeutic target for the treatment of prostate cancer." (PMID 41214670, 2025). "However, the roles of FOXD1 in prostate cancer remain largely unknown." (PMID 41214670, 2025). "Both FOXD1 and FOXP1 have been reported as activators of Wnt/β-catenin signaling in prostate cancer and diffuse large B cell lymphoma, respectively 28,29." (PMID 38684876, 2024). "The expression levels of HK2 and FOXD1 mRNA were both increased in cancer group compared to those in normal group, and HK2 and FOXD1 mRNA levels were both increased after hypoxic treatment in prostate cancer PC-3, 22Rv1, DU145, and LNCaP cells." (PMID 41214670, 2025). "Moreover, there was no analysis of the clinical correlation between FOXD1 expression and glycolysis-related molecule levels (e.g., HK-2 and LDHA) in clinical prostate cancer samples, which weakens the clinical translational value of the study’s findings." (PMID 41214670, 2025).
head and neck squamous cell carcinoma (9 papers, 2021 to 2024). A squamous cell carcinoma that arises from any of the following anatomic sites: lip and oral cavity, nasal cavity, paranasal sinuses, pharynx, larynx, and salivary glands. "This study evaluated the expression of FOXD1 and its role in head and neck squamous cell carcinoma (HNSCC)." (PMID 33403027, 2021). "Finally, we observed two ISRS model genes (CAMTA2 and FOXD1) with abundant research value in oncology, which have been proven as oncogenes in head and neck squamous cell carcinoma or colon cancer." (PMID 38512513, 2024). "Another study by us showed that the expression of FOXD1 could serve as an independent prognosticator for head and neck squamous cell carcinoma, which indicated that adding the expression of FOXD1 into the prognostic assessment tool, such as TNM system, could improve the prognostic prediction." (PMID 38553712, 2024). "Mammalian FoxD1 is related to apoptosis, as the knockdown expression of FoxD1 facilitates apoptosis in HNSCC (head and neck squamous cell carcinoma) cells." (PMID 39057213, 2024). "However, there is limited information regarding FOXD1 expression in head and neck squamous cell carcinoma (HNSCC)." (PMID 36983712, 2023). "Forkhead box D1 (FOXD1) belongs to the FOX protein family, which has been found to function as a oncogene in multiple cancer types, but its role in head and neck squamous cell carcinoma (HNSCC) requires further investigation." (PMID 37563111, 2023).
oral cancer (9 papers, 2020 to 2025). "It has been reported that FOXD1 is extensively detected in oral cancer tissues and associated with poor outcome in patients receiving irradiation since it may lessen anti-cancer radiotherapy effectiveness and immune surveillance." (PMID 41214670, 2025). "Moreover, our data showed that the level of FOXD1 transcript is causally relevant to the effective dosage of irradiation in a panel of oral cancer cell lines." (PMID 32967107, 2020). "Here we show that FOXD1, a gene encoding forkhead box d1 (Foxd1), is significantly upregulated in primary tumors compared to normal tissues and serves as a poor prognostic marker in oral cancer patients receiving radiotherapy." (PMID 32967107, 2020). "Moreover, our data showed that the endogenous protein and mRNA levels of FOXD1 are causally associated with the cell viability and colony-forming ability detected after 24 h post-treatment with irradiation at 8 Gy in oral cancer cell lines HSC2, HSC3, HSC4 and SAS." (PMID 32967107, 2020). "lncRNA CYTOR, which promotes EMT and chemoresistance, has been reported to be regulated by FOXD1 transcription in oral carcinoma." (PMID 37563111, 2023). "In oral cancer cells, FOXD1 promotes the malignant progression of cells by upregulating G3BP2 expression via directly binding to its promoter." (PMID 37906341, 2023). "Our results demonstrate that FOXD1 is highly expressed by primary tumors compared to the adjacent normal tissues and serves as a poor prognostic marker in oral cancer patients receiving irradiation therapy." (PMID 32967107, 2020). "The FOXD1 knockdown (FOXD1-KD) dramatically suppressed the colony-forming ability of oral cancer cells after irradiation treatment." (PMID 32967107, 2020). "Our data demonstrate that the upregulation of FOXD1 compared to other FOXDs is extensively detected in primary tumors and significantly correlated with a poorer clinical outcome in oral cancer patients." (PMID 32967107, 2020). "Since radiotherapy is commonly used to treat oral cancer patients, we next dissected the correlation between FOXD1 expression and irradiation responsiveness in oral cancer." (PMID 32967107, 2020). "Knockdown of FOXD1 could significantly inhibite the colony-forming ability of oral cancer cells after radiotherapy and enhance the expression of TXNIP via the JAK-STAT signalling pathway." (PMID 39494294, 2024). "Moreover, the knockdown of FOXD1 impairs the colony-forming abilities of oral cancer cells after radiation treatment." (PMID 35886008, 2022). "This study provides us the evidence that FOXD1 promotes oral cancer progression." (PMID 34028536, 2021). "The targeting of FOXD1 might be a good strategy to enhance the radiosensitivity of oral cancer cells via downregulating G3BP2-related pathways and upregulating the TXNIP-associated cellular functions." (PMID 32967107, 2020). "This study is the first to document the oncogenic role of FOXD1 in oral cancer." (PMID 32967107, 2020).
oral cancer (continued). "Here, we found that FOXD1 knockdown is concurrently accompanied with a reduced expression of PD-L1, a critical suppressor for T cell function through the binding with PD-1, in oral cancer cells with poorer radiosensitivity." (PMID 32967107, 2020). "Our findings demonstrate that FOXD1 may play a pivotal role in conferring radioresistance, which might provide a new strategy to combat the irradiation-insensitive oral cancer cells via therapeutically targeting FOXD1 activity." (PMID 32967107, 2020). "Similarly, our results demonstrate that FOXD1 knockdown enhances the radiosensitivity of oral cancer cells via activating the IFN-α and IFN-γ-responsive pathways." (PMID 32967107, 2020). "Therefore, the therapeutic targeting of FOXD1 might be a new strategy to potentiate the efficacy of irradiation in treating oral cancer." (PMID 32967107, 2020). "By using GSE42734 dataset, we found that the mRNA levels of FOXD1 and PD-L1-coding gene CD274 are positively correlated in primary tumors derived from oral cancer patients." (PMID 32967107, 2020). "Similar to FOXD1, the mRNA levels of G3BP2 in HSC4 cells were higher than other oral cancer cell lines." (PMID 32967107, 2020). "In addition, our results reveal that FOXD1 upregulation is accompanied with an enhanced activity of E2F, probably due to the dissociation with hyper-phosphorylated Rb protein, which has been shown to promote cell cycle progression and desensitize oral cancer cells to irradiation." (PMID 32967107, 2020). "In oral cancer tissues derived from the GSE42734 dataset, we found that the expression of FOXD1 and TXNIP is significantly (p = 0.029) inversed." (PMID 32967107, 2020). "Notably, FOXD1 has been reported to be an important transcriptional factor that promotes drug resistance and epithelial-to-mesenchymal transition (EMT) in oral carcinoma." (PMID 37563111, 2023). "The data showed that luciferase activities are significantly (p < 0.01) increased after FOXD1 knockdown, indicating a negative correlation between FOXD1 expression and interferon actions in oral cancer." (PMID 32967107, 2020). "LncRNA CYTOR regulates mitochondrial metabolism and glycolysis of oral cancer cells via HNRNPC-mediated ZEB1 stabilization in oral squamous cell carcinoma, and the level of CYTOR could be upregulated by forkhead box D1 to promote EMT and chemoresistance in oral squamous cell carcinoma." (PMID 36814556, 2023). "Robustly, FOXD1, but not FOXD2, FOXD3 and FOXD4, was significantly (p < 0.01) upregulated in primary tumors compared to normal adjacent tissues derived from oral cancer patients deposited in the GSE42743 dataset." (PMID 32967107, 2020).
oral squamous cell carcinoma (7 papers, 2020 to 2025). "For instance, in oral squamous cell carcinoma, FOXD1 promotes the epithelial–mesenchymal transition (EMT) by activation of SNAI2." (PMID 35954332, 2022). "Immunohistochemistry revealed that FOXD1 protein level was higher in oral squamous cell carcinoma than that in normal oral epithelium." (PMID 34028536, 2021).
non-small cell lung carcinoma (6 papers, 2019 to 2024). A group of at least three distinct histological types of lung cancer, including non-small cell squamous cell carcinoma, adenocarcinoma, and large cell carcinoma. "In non-small cell lung cancer, FOXD1 translocation to the nucleus to activate Gal-3 expression is inhibited by inactivation of ERK or depletion of ERK1 or ERK2." (PMID 38827805, 2024). "A microarray analysis assessed the levels of FOXD1 mRNA in non-small cell lung cancer (NSCLC) and found that the levels were significantly associated with patient survival by disturbing cell proliferation." (PMID 36983712, 2023). "FOXD1 silencing inhibits cell proliferation in non-small cell lung cancer, while FOXD1 over-expression is related to poor prognosis in the same cancer type." (PMID 30627052, 2019).
glioblastoma (5 papers, 2022 to 2024). The most malignant astrocytic tumor (WHO grade IV). "USP21 promotes self-renewal and tumorigenicity of mesenchymal glioblastoma stem cells by deubiquitinating and stabilizing FOXD1." (PMID 38829550, 2024). "Recent studies suggest that Forkhead box D1 (FOXD1) plays an indispensable role in maintaining the mesenchymal (MES) properties of glioblastoma (GBM) stem cells (GSCs)." (PMID 35974001, 2022).
lung squamous cell carcinoma (5 papers, 2021 to 2024). "However, litter is known about the role of FOXD1 in the progression of lung squamous cell carcinoma (LUSC)." (PMID 35607308, 2022). "Importantly, miR-30a-5p directly binds to the 3′-UTR of FOXD1 and suppresses its expression in several types of cancer cells, e.g., lung squamous cell carcinoma, pancreatic ductal adenocarcinoma, osteosarcoma, and ovarian cancer." (PMID 35886008, 2022).
osteoarthritis (5 papers, 2019 to 2023). A noninflammatory degenerative joint disease occurring chiefly in older persons, characterized by degeneration of the articular cartilage, hypertrophy of bone at the margins and changes in the synovial membrane. "A study proved that knockdown of FOXD1 facilitated the senescence of human mesenchymal stem cells and that intra-articular injection of a lentiviral vector encoding FOXD1 reduces the development of mouse osteoarthritis." (PMID 37563111, 2023). "Gene therapy with lentiviral vectors encoding YAP or FOXD1 prevented cellular aging and attenuated osteoarthritis in mice." (PMID 30933975, 2019). "Numerous studies have shown that FOXD1 performs multiple roles in normal physiological function as well as disease progression, as is the case in kidney development, osteoarthritis, recurrent pregnancy loss, and malignant biological functions of various tumors." (PMID 36057597, 2022). "Moreover, intra-articular administration of lentiviral vector encoding YAP or FOXD1 attenuated the development of osteoarthritis in mice." (PMID 30933975, 2019). "Overexpression of YAP or FOXD1 alleviated the senescence of aged MSCs and attenuated the development of osteoarthritis in mice." (PMID 31881006, 2019). "Lentiviral gene transfer of YAP or FOXD1 can rejuvenate aged hMSCs and ameliorate osteoarthritis symptoms in mouse models." (PMID 30933975, 2019). "The Hippo signalling effector YAP and the transcription factor FOXD1 play a role in alleviating cellular senescence and osteoarthritis, identifying the YAP-FOXD1 axis as a potential therapeutic target for aging-associated disorders." (PMID 30933975, 2019). "Given the ability of YAP or FOXD1 to rejuvenate senescent MSCs, we hypothesized that intra-articular injection of lentiviral vectors expressing YAP or FOXD1 might exert a therapeutic effect on osteoarthritis." (PMID 30933975, 2019). "As expected, ACLT induced the accumulation of P16-positive senescent cells in the articular cartilage, particularly in the superficial zone of cartilage, of the osteoarthritis mice, which was accompanied by decreased levels of YAP and FOXD1." (PMID 30933975, 2019). "To test this, we performed an anterior cruciate ligament transection (ACLT) surgery widely used to trigger osteoarthritis in mice and then administrated the lentiviruses expressing flag-tagged Luc, YAP, or FOXD1 intra-articularly." (PMID 30933975, 2019). "Our data suggest that YAP and its downstream target FOXD1 are novel suppressors of hMSC senescence and that the YAP–FOXD1 regulatory axis represents a potential therapeutic target for osteoarthritis." (PMID 30933975, 2019). "To validate a role of hMSC senescence in driving osteoarthritis, we injected young hMSCs, RS hMSCs, and RS hMSCs overexpressing YAP or FOXD1, respectively, into the joints of immunodeficient mice and performed histological assessment of the joints 1 month later." (PMID 30933975, 2019). "However, no osteoarthritis-related features manifested in the joints transplanted with young hMSCs or RS hMSCs overexpressing YAP or FOXD1." (PMID 30933975, 2019).